RN7SKP74 (RN7SK pseudogene 74)
Gene: Miscellaneous RNA gene on chromosome 20 (18,295,143 to 18,295,451, reverse strand). Ensembl gene ENSG00000199719.
Homologues: Orthologues: chimpanzee 7SK (97% identical), mouse Gm55136 (53% identical). Paralogues in human: RN7SKP90 (77% identical), RN7SKP79 (76% identical), 7SK (76% identical), RN7SKP204 (75% identical), RN7SKP137 (75% identical), RN7SKP203 (75% identical), RN7SKP163 (74% identical), RN7SKP38 (74% identical), RN7SKP9 (74% identical), RN7SKP255 (74% identical), RN7SKP37 (74% identical), RN7SKP20 (74% identical), and 284 more.